IL17A (interleukin 17A)
Diseases named in the same sentence as IL17A in open-access papers (continued):
Sharing a sentence is not in itself a finding about the gene and the disease.
AIDS (28 papers, 2011 to 2024). A syndrome resulting from the acquired deficiency of cellular immunity caused by the human immunodeficiency virus (HIV). "In this study, we aim to elucidate the activity of IL-17A in the protection against Cryptococcus neoformans, an opportunistic fungus that causes fatal meningoencephalitis among AIDS patients." (PMID 30409128, 2018). "IL-17A is involved in maintaining the integrity of the epithelial barrier, and depletion of gut-associated lymphoid tissue Th17 and Th1/Th17 lymphocytes was shown to be the main cause of chronic immune activation and non-AIDS-related comorbidities in infected individuals." (PMID 29467764, 2018). "In AIDS, Tr-Gal9, IL-17A, and TGFα showed the high Youden index of more than 1.900." (PMID 33143141, 2020). "In support of the protective role of proinflammatory cytokines, a later study also showed that HIV/AIDS patients who have survived cryptococcal meningoencephalitis exhibited higher CSF levels of IL-8, IL-12p40, IL-17A, TNF-α, INF-γ and serum TNF-α compared to non-survivors." (PMID 36557672, 2022).
eczema (28 papers, 2010 to 2026). "Additionally, inhibition of IL-17A—which plays a role in mucosal defense—may compromise skin barrier function and increase the risk of eczema, particularly in sensitive areas such as the face." (PMID 41306762, 2025).
graft versus host disease (28 papers, 2012 to 2025). An immune system disorder that occurs after allogeneic hematopoietic stem cell transplant and is a reaction of donor immune cells against host tissues. "This same GG genotype has been associated with higher serum levels of IL-17A for graft versus host disease after allogeneic hematopoietic stem cell transplantation." (PMID 33868301, 2021). "Thus, in a model of graft-versus-host disease, IL-17A deficiency elicited an amplified Th1 response with high IFN-γ levels and greater severity of the disease." (PMID 22577359, 2012). "These works also identified IL-17A as the main path linking microbiota to Graft-Versus-Host Disease (GVHD)." (PMID 35371048, 2022). "We showed that IL-17A-producing Tregs are the key mediators in the treatment of graft-versus-host disease." (PMID 27610554, 2017). "The participation of IL-17A has also been described in the acute rejection of organ transplants and graft versus host disease." (PMID 23843069, 2013). "IL-17A and IL-17F cytokines are important regulators of acute graft-versus-host-disease (GVHD)." (PMID 32251446, 2020). "IL-17A is a potent proinflammatory mediator and is involved in the pathogenesis of autoimmune diseases, allergic responses, and other immune cell mediated diseases including allograft rejection, sepsis, and graft versus host disease (GvHD)." (PMID 28293262, 2017). "In studies of graft-versus-host disease (GVHD), IL-17A acts in a protective fashion and may play a role in the pathogenesis of liver pathology." (PMID 25133396, 2014).
lymph node metastasis (28 papers, 2011 to 2026). "We examined the clinical data of 77 patients with PCa and lymph node metastasis (LN+) and then evaluated the levels of IL-17A and IL-17RA expression in the prostate and LN+." (PMID 37760548, 2023). "IL17A+ cell was found in CCA intratumoral areas which was correlated with lymph node metastasis, intrahepatic metastasis, and tumor progression to advanced stages." (PMID 33579265, 2021). "The elevated serum and local IL-17A levels were positively correlated with lymph node metastasis and advanced clinical stages of TSCC patients." (PMID 28035060, 2017). "Notably, more patients in IL-17A low expression group had lymph node metastasis than IL-17A high expression group (73.3% vs 35%, P = 0.025)." (PMID 31159823, 2019). "In addition, IL-17A rs2275913 polymorphism was related to TNM stage III+IV and lymph node metastasis." (PMID 31682719, 2019). "In the present study, we demonstrate that the levels of IL-17A in serum and tumor samples are significantly increased in TSCC patients and positively correlate with lymph node metastasis and tumor clinical stages of TSCC." (PMID 28035060, 2017). "Patients with lymph node metastasis have higher serum concentrations of IL-17A, compared with those without node metastasis." (PMID 32489459, 2020). "After quantification of immunohistochemical stainings of 76 patients, we found that the expressions of IL-17A were higher in patients with lymph node metastasis of N1 and N2 stages than N0 (without metastasis) stage." (PMID 28035060, 2017).
pneumococcal infection (28 papers, 2010 to 2025). Infections with bacteria of the species streptococcus pneumoniae. "In Streptococcus pneumoniae infection, pneumolysin can induce the secretion of IL-17A and IFN-γ via NLRP3 inflammasome signaling." (PMID 30105037, 2018). "B cell KO mice have been studied previously for IL-17A induced inflammation in Pneumococcal infections." (PMID 26079807, 2015). "To investigate the role of IL-17A in the accumulation of neutrophils in the lung, we measured IL-17A levels during pneumococcal infection established with Type 3 S." (PMID 24408967, 2014). "In this study, we found that γδ T cells, but not αβ T cells, were required for neutrophil recruitment and activity in host defence against pneumococcal infection via IL-17A production." (PMID 24408967, 2014). "An important role for the alveolar macrophage in the early hours of pneumococcal infection has been highlighted previously in murine models and IL-17A from innate sources are likely to be involved." (PMID 23555269, 2013). "Both IL-17A and IFN-γ are required for protective immunity to pneumococcal infection and intranasal infection of mice with PLY-deficient pneumococci induced significantly less IFN-γ and IL-17A in the lungs compared to infection with wild-type bacteria." (PMID 21085613, 2010). "Here we show that PLY strongly enhances the secretion of IFN-γ by splenocytes in vitro and is required for IFN-γ and IL-17A responses during pneumococcal infection in vivo." (PMID 21085613, 2010). "IL-1β plays a key role in promoting IL-17A and was previously shown to mediate protection against pneumococcal infection." (PMID 21085613, 2010). "For instances, macrophages ATF3 plays key roles in host survival and pathogen clearance through controlling intracellular calcium level and ATP homeostasis, and consequently stimulating interleukin 17A (IL-17A) expression during streptococcus pneumoniae infection." (PMID 37645012, 2023). "In addition, it was reported that IL-27 production in an IFNAR-signaling-dependent manner induced by IFV impairs IL-17A-producing γδ T cells, leading to a reduced neutrophil response and resistance to a secondary pneumococcal infection." (PMID 32660087, 2020). "Mice deficient in IL-27 receptor were resistant to secondary pneumococcal infection and generated more IL-17A-producing γδ T cells but not αβ T cells, thereby leading to enhanced neutrophil response during the early phase of host defence." (PMID 24408967, 2014). "Finally, neutralization of IL-27 or administration of IL-17A restored the role of γδ T cells in combating secondary pneumococcal infection." (PMID 24408967, 2014). "We found that inoculation of exogenous IL-27 could significantly down-regulate IL-17A production and the percentage of IL-17A-producing γδ T cells in the lungs of IFNAR-deficient mice after secondary pneumococcal infection." (PMID 24408967, 2014). "However, influenza virus infection selectively attenuated innate IL-17A production by γδ T cells upon secondary pneumococcal infection, which contributed to the development of postinfluenza pneumococcal pneumonia." (PMID 24408967, 2014). "These are the first data of which we are aware to describe the relation of nasal carriage of a pathogenic organism and lung IL-17A responses in humans and together support a role for effector IL-17A+ CD4+ memory T-cell responses in the defence of the lung against pneumococcal infection in adults." (PMID 23555269, 2013). "However, it remains to be ascertained whether S. mitis serotype 5-induced IL-17A/Th17 immunity plays a direct role in protection against pneumococcal infection, which will be addressed in our future studies by using IL-17 knockout mice." (PMID 33953733, 2021). "Data from our group and others indicate that α-GalCer provides prophylactic protection against lethal pneumococcal infections (an effect that depends on IFN-γ, IL-17A, and neutrophils) (31, –, 33)." (PMID 27803187, 2016).
pneumococcal infection (continued). "Both IL-17A and IFN-γ are essential to protective immune response against pneumococcal infection." (PMID 30105037, 2018). "Therefore, we reported what we believe to be a novel negative role of IL-27 in IL-17A production by γδ T cells upon secondary pneumococcal infection." (PMID 24408967, 2014). "Having shown that PLY enhanced the secretion of cytokines, including IFN-γ and IL-17A by splenocytes stimulated in vitro, we next determined the contribution of PLY to pneumococcus-induced cytokine production using two different murine models of pneumococcal infection in vivo." (PMID 21085613, 2010). "Pneumococcal-responding IL-17A-secreting CD4+ T-cells have not been described in the adult human lung and it is unknown whether they can be elicited by carriage and protect the lung from pneumococcal infection." (PMID 23555269, 2013).
viral myocarditis (28 papers, 2011 to 2026). Myocarditis that is caused by an infection with a viral agent. "The AA genotype of the IL-17A rs2275913 SNP and a haplotype comprising rs2275913 A/rs3819025 G/rs3748067 G of the IL-17A gene were associated with a higher risk of viral myocarditis in humans." (PMID 38139455, 2023). "Moreover, the AA genotype of the IL-17A rs2275913 SNP was linked to higher serum IL-17A levels compared with GG/AG genotypes, and these higher serum IL-17A levels correlated with cardiac damage in viral myocarditis patients." (PMID 38139455, 2023). "In autoimmune and viral myocarditis, IL-17A orchestrates fibroblast activation through epithelial-mesenchymal transition 30, 31, TGF-β synergy, and ECM cross-linking." (PMID 41356193, 2026). "Interleukin (IL)-17A produced by Th17 cells is dispensable for viral myocarditis but essential for the progression to dilated cardiomyopathy (DCM)." (PMID 23977238, 2013). "However, in IL-17A-deficient mice, IL-22 exacerbates CVB3-induced acute viral myocarditis." (PMID 25547181, 2014). "Th17 cells play a crucial role in the development of TLSs by secreting cytokines, such as IL-17 and IL-22.147,551 IL-17A+ PDPN+ T cells are present within TLSs in the myocardial tissue of viral myocarditis." (PMID 39198425, 2024). "To explore the relationship between IL-17A and ECM degradation from chronic viral myocarditis to DCM, we examined the expression of the ADAMTS-1 and MMPs/TIMPs proteins in the myocardium using western blotting." (PMID 23977238, 2013). "Similarly, in the chronic viral myocarditis model, we determined that over the course of the progression of viral myocarditis to DCM, the lack of IL-17A stimulation leads to the significant downregulation of IL-6." (PMID 23977238, 2013).
bacterial pneumonia (27 papers, 2010 to 2025). Acute infection of the lung parenchyma caused by bacteria (e.g., Streptococcus pneumoniae, Haemophilus influenzae, Chlamydia pneumoniae, Mycoplasma pneumoniae, and Legionella pneumophila). "Intestinal commensal flora enhances host defense against bacterial pneumonia by adding interleukin 17 A(IL17A) and regulating GM-CSF signaling." (PMID 37038223, 2023). "One of the main mechanisms of IL-17A in controlling bacterial pneumonia in mouse models is neutrophil recruitment." (PMID 28806403, 2017). "Elucidating the source of IL-17A will enhance our understanding of its role in bacterial pneumonia." (PMID 28806403, 2017). "In models of bacterial pneumonia IL-17R signaling or IL-17A is required for pathogen clearance." (PMID 22514650, 2012). "Similarly, IL-17A significantly decreased in bacterial pneumonia (Δ = 8.6, 95% CI 1.4–15.0)." (PMID 40869413, 2025).
dengue (27 papers, 2008 to 2025). "Our results for the association between IL-17A levels and dengue severity are consistent with recent scientific reports." (PMID 33322218, 2020). "Elevated expression of IL-17A has been observed in DHF than DF; similar reports have been reported that IL-17 has been associated with severe dengue." (PMID 34447698, 2021). "Fixed single-cell RNA profiling identified IL-17A/F-producing γδ T cells, ILC3s, and Th17 cells, cooperative roles of M1- and M2-like macrophages, and dual roles of neutrophils during severe dengue." (PMID 40127923, 2025). "We found that IL-17A produced by γδ T cells in the small intestine was another critical factor enabling severe dengue at the cytokine level." (PMID 37939119, 2023). "Previous dengue infection was associated with increased concentrations of IL-17A and IL-1β but decreased concentrations of epidermal growth factor (EGF), and IL-8 compared to dengue-naive individuals." (PMID 37943879, 2023). "The results from individuals with previous Zika infection (DV-ZV+) were comparable to those in previously dengue-naive individuals, except for IL-10 and IL-17A (which were elevated in patients with previous Zika infection)." (PMID 37943879, 2023). "Several previous studies reported increased IL-17A levels or activation of γδ T cells in patients with severe dengue." (PMID 37939119, 2023). "The possibility of immunotherapy against severe dengue by targeting IL-6 or IL17A should be carefully considered." (PMID 37939119, 2023). "Several of these cytokines have been identified as markers of dengue in humans, including IL-12, IL-13, IL-17A, G-CSF, IFNγ, and TNFα." (PMID 29559699, 2018). "Higher levels of IL-17A have been detected in dengue patients; however, whether these higher levels contribute to severe disease requires further study." (PMID 37939119, 2023). "Whereas in secondary cases IL-17A was associated with dengue severity, there was no such association for IL-17F." (PMID 33322218, 2020). "The increased production of IL-17A, in a synergic effect with other inflammatory mediators, could in turn result in severe dengue pathology during secondary infections." (PMID 33322218, 2020). "Several studies have found that IL-6, IL-17A, IFN-α, IL-1β, IL-10, and TNF-α play different roles in dengue disease, but we didn't know which factor play key roles or even correlated with IL-37b and other factors." (PMID 37024713, 2023). "Within dengue severity IL-1β, IL-10 (Th1/2), and IP-10 (Th1) have been upregulated in DHF/DSS than DF, and IL-6 (Th1/Th2) and IL-17A (Th17) in DHF than DSS." (PMID 34447698, 2021). "A clinical study should be conducted to ascertain whether IL-17A and γδ T cells, as well as other IL-17A-producing cells, neutrophils, and MMP-8, are involved in the pathogenesis of severe dengue in humans." (PMID 37939119, 2023). "Our first priority was to compare the levels of IL-1b, IL-2, IL-4, IL-6, IL-8, IL-10, IL-12p70, IL-17A, IL-33, CD14, CD54, CD62E, CD62L, CD62p, CD106, CD121b, CD154, CD178, GM-CSF, IFN-g, MIF, ST2 and TNF in plasma samples of dengue group, OF group and Healthy group." (PMID 33809042, 2021). "But unexpectedly, we could not detect IL-1β, IL-17A or TNF-α in dengue samples because of off-target." (PMID 37024713, 2023). "Notably, the α-IL-17A Ab also suppressed MMP-8, but not MMP-3, suggesting that MMP-3 plays less of a role in severe dengue." (PMID 37939119, 2023).
food allergy (27 papers, 2012 to 2025). Gastrointestinal disturbances, skin eruptions, or shock due to allergic reactions to allergens in food. "One exception was IL-17A, a cytokine known to be associated with food allergy." (PMID 29967609, 2018). "IL-17A levels were significantly positively related to IFN-γ levels in children with food allergies (r=0.79) and in healthy children (r=0.98)." (PMID 38090557, 2023). "The mean IL-17A level (0.97 ± 0.09 pg/ml) in the food allergy group was higher than that in the healthy group (0.69 ± 0.09 pg/ml)." (PMID 38090557, 2023). "It has been suggested that IL-17A plays a role in the regulation of food allergy and is a potential biomarker of tolerance to food allergens; however, the role of IL-17F in food allergy is not well understood." (PMID 33571165, 2021). "However, induction of a food allergy to OVA led to significant upregulation of Il17a along with elevated expression of Il1b and Il12a, indicating that allergic inflammation augments the inflammatory response to C. albicans in the glandular stomach." (PMID 39347572, 2024). "While IL-17A signaling has been implicated in both allergic inflammation and PSO, there was less enrichment of genes involved in the proallergic IL-4 and IL-13 responses, despite the fact that patients with SAM syndrome often develop food allergies and have elevated levels of IgE." (PMID 34905516, 2022). "The salivary IL-17A and IFN-γ levels in children with food allergies were higher than those in healthy children." (PMID 38090557, 2023). "This study explored the levels of and relationship between IL-17A and IFN-γ in the saliva of children with food allergies, which will form the basis for further mechanistic discoveries as well as prevention and treatment measures for food allergies." (PMID 38090557, 2023). "A general linear model was used to analyze whether the salivary IL-17A and IFN-γ levels in the food allergy group differed from those in the control group." (PMID 38090557, 2023). "The levels of transcription factor FoxP3 and cytokines TGF-β, IL-17A, and IL-23 were not measured in the children with food allergy." (PMID 30651897, 2018).
hepatitis C (27 papers, 2017 to 2025). "In humans, CD8αα MAIT cells isolated from adult PMBCs secreted more IL-17A after stimulation with PMA/ionomycin than CD8αβ cells, suggesting an active role in immunity and tissue inflammation, possibly as tissue infiltrates in inflammatory arthritis or the liver in hepatitis C infection." (PMID 31404411, 2019).
joint disease (27 papers, 2010 to 2026). "Cytokines like IL-17A have been consistently found to be elevated in psoriatic lesional skin, and therapeutic antibodies to IL-17 have demonstrated efficacy in treating psoriatic skin and joint disease." (PMID 36118416, 2022). "Inhibition of IL-17A by neutralizing antibodies has been shown to improve the signs and symptoms of joint disease in patients with PsA." (PMID 30053825, 2018). "Aside from tumor necrosis factor (TNF), interleukin-17A (IL-17A) has been identified as a key cytokine in psoriatic skin and joint disease." (PMID 30053825, 2018). "Despite a lack of association between baseline levels of the IL-23 effector cytokines IL-17A, IL-17F, and IL-22 with joint disease activity in the current analyses, improvements in this domain were observed through 2 years and correlated with baseline levels of acute phase proteins." (PMID 39493888, 2024). "We hypothesized that IL-17A inhibition in this subset of patients can intercept the link between skin and joint disease and resolves pain and inflammatory changes." (PMID 31349876, 2019). "Interestingly, CD4+ and CD8+ T cells in the feet during the acute phase of disease expressed both IL-17A and IL-17F, indicating that IL-17RA signaling may require binding of both IL-17A and IL-17F isoforms in the context of alphavirus-induced arthropathy." (PMID 35143591, 2022). "There are FDA-approved biologics targeting IL-17A, such as secukinumab, ixekizumab, bimekizumab, and brodalumab, raising the possibility that such drugs might find utility in the treatment of chronic CHIKV arthropathy." (PMID 35254128, 2022).